PIK3CA (phosphatidylinositol-4,5-bisphosphate 3-kinase catalytic subunit alpha)
Diseases named in the same sentence as PIK3CA in open-access papers (continued):
Sharing a sentence is not in itself a finding about the gene and the disease.
tumor (continued). "In the first‐in‐human clinical trial of the KAT6 inhibitor PF‐07248144, researchers performed preliminary biomarker analyses of circulating tumor DNA (ctDNA) mutation profiling at baseline, including ESR1 and PIK3CA/PTEN/AKT1 genes." (PMID 41357671, 2025). "Diagnostic tumour material was, whenever sufficient, analysed for RAS, BRAF, and PIK3CA mutations, and MMR-status." (PMID 40437037, 2025). "Our previous investigations with a PDAC mouse model revealed that downregulation of PIK3CA in tumor cells enhances their recognition and elimination by T cells." (PMID 40067762, 2025). "PIK3CA/AKT1/PTEN tumor alterations were detected in 24 patients (33.8%) receiving capivasertib–fulvestrant and in 22 patients (34.9%) receiving placebo–fulvestrant." (PMID 40346047, 2025). "Two samples with PIK3CA mutations (one with PIK3CA only and one with BRAF V600E/PIK3CA) were confirmed to be one malignant tumor and one benign tumor." (PMID 40586006, 2025). "Mutations in PIK3CA and other alterations in the PI3K/AKT pathway contribute to tumor growth and treatment resistance." (PMID 39941081, 2025). "As expected, POLEmut tumors exhibited a higher tumor mutation burden (TMB) than the other subtypes, with notable mutations in PIK3CA (60.0 %) and PTEN (60.0 %)." (PMID 40199194, 2025). "These metabolic adaptations correlate with anatomical subtypes (e.g., ERBB2-amplified iCCA vs. PIK3CA-mutant extrahepatic tumours) and influence chemotherapy/targeted therapy efficacy." (PMID 40861435, 2025). "Hyperactivation of the PI3K/AKT/mTOR pathway occurs in approximately 35–50% of TNBC cases, primarily driven by activating mutations in PIK3CA (15–25%) and AKT1 (5–10%), or the loss of PTEN (30–50%), leading to tumor aggressiveness and therapeutic resistance." (PMID 41516322, 2025). "The mutational profile of CRC tumors, including KRAS, NRAS, BRAF, PIK3CA, and AKT1 gene mutation and MSI status significantly influences the characteristics of the tumor microenvironment (TME) and directly impacts patient prognosis." (PMID 40724985, 2025). "Well-known pathogenic mutations were only detected in the tumor tissues: p.G12D in KRAS in patients S428 and S430, and p.E545K in phosphatidylinositol-4,5-bisphosphate 3-kinase catalytic subunit alpha (PIK3CA) in patient S170." (PMID 41301905, 2025). "The PI3K/AKT/mTOR pathway, often altered through PIK3CA mutations or PTEN loss, regulates tumor growth and contributes to resistance against upstream inhibitors." (PMID 41228293, 2025). "Liquid biopsy through circulating tumour cells (CTC) and circulating tumour DNA (ctDNA) analyses is becoming a promising approach for identifying mutation status, such as PIK3CA and ESR, which have sped up treatment decisions." (PMID 41228202, 2025). "The relatively high prevalence of PIK3CA alterations in ATC (~23%) underscores the role of PI3K pathway activation in tumor dedifferentiation and progression to more aggressive phenotypes." (PMID 40363930, 2025). "In PIK3CA-mutant xenografts, it significantly suppressed tumor growth while maintaining glucose homeostasis." (PMID 40723456, 2025). "Even so, previous studies have shown high concordance between plasma- and tissue-based genotyping in BC, and plasma–based PIK3CA testing is now recognized as a clinically supported option when tumor tissue is unavailable." (PMID 41415546, 2025).
tumor (continued). "More recently the AKT inhibitor (AKTi) capivasertib combined with fulvestrant also increased benefit versus fulvestrant alone in a broader segment of patients with tumour alterations in PIK3CA, PTEN or AKT-18." (PMID 40263319, 2025). "Next, we evaluated the recognition of tumor cells that can express and process the mutant PIK3CA protein by the two specific 4367 PIK3CAN345K-TCRs." (PMID 41410746, 2025). "The catalytic subunit p110α regulated by the PIK3CA gene of PI3K is mutated, causing an hyperactivation of this gene, while there is a loss of PTEN, resulting in tumor growth." (PMID 40227634, 2025). "CDx biomarkers (including BRAF, EGFR, PIK3CA, and RAS mutations) and other tumor profiling biomarkers (including clinically relevant alterations and TMB) were represented in marker positive samples diluted with lineage matched marker negative samples." (PMID 40804002, 2025). "To further investigate the impact of PIK3CA on bone metastasis of NSCLC, we established a metastatic tumor mouse model by intracardiac injection of wild-type and mutant PIK3CA NSCLC cells." (PMID 40328748, 2025). "There was also an enrichment of PIK3CA and MAP3K1 mutations in mG1 samples, indicating the specificity of this mechanism in tumor development." (PMID 40740860, 2025). "Our study underscores the complexity of CRC and the pivotal role of KRAS, BRAF, and PIK3CA variations in tumor progression and outcomes in Iraq's Kurdistan Region, highlighting the importance of molecular profiling in clinical care." (PMID 40949797, 2025). "To increase the sensitivity by simultaneously tracking multiple tumor mutations, we additionally included genes in the panel that are commonly altered in MLS, such as PIK3CA and the TERT promoter region." (PMID 39980272, 2025). "Conversely, in the low-risk group, PIK3CA, PTEN, and ARID1A exhibit the highest mutation frequencies, suggesting a correlation with the initial stages of tumor development." (PMID 40463372, 2025). "Collectively, these trials highlight the growing interest in PI3K inhibitors as tumor-agnostic therapies, reinforcing PIK3CA as a promising biomarker for targeted treatment across a wide range of cancers." (PMID 40576713, 2025). "With Alp as an additional chemotherapeutic agent, Cr@PD‐Alp exhibits superior potency toward the NSG mice bearing an MDA‐MB‐231 PIK3CA (H1047R/+) tumor and can inhibit tumor metastasis to the lungs." (PMID 38899741, 2025). "It was shown that right‐sided tumours exhibit lower responsiveness to anti‐EGFR treatment and higher mutation rates in genes like BRAF, PIK3CA, and KRAS, suggesting potential underlying reasons for this association." (PMID 40302146, 2025). "Systemic therapy use, however, can be dependent on molecular characterization, such as HER2 expression status and mutational status of ERBB2, PIK3CA, AKT1, PTEN, and ESR1, particularly in the primary tumor." (PMID 41149070, 2025). "APC is central to the Wnt signaling pathway, and its mutation leads to uncontrolled cell proliferation, while PIK3CA mutations activate the PI3K-Akt pathway, which promotes tumor cell survival and growth." (PMID 40936932, 2025).
tumor (continued). "Capivasertib–fulvestrant is approved in Japan for the treatment of patients with one or more tumor biomarker alterations (PIK3CA, AKT1 or PTEN)." (PMID 39379782, 2025). "During this week, rapid sequencing of the patient’s tumor was completed, identifying H3K27M and PIK3CA mutations." (PMID 41155119, 2025). "Mutations in the PIK3CA gene are a common mechanism of PI3K activation in various cancers, including LC, leading to uncontrolled cell growth and tumor development." (PMID 41217667, 2025). "Mutations in canonical oncogenes such as BRAF, KRAS, PIK3CA, and ALK function as dominant molecular drivers, defining biologically distinct tumor subsets characterized by specific therapeutic liabilities." (PMID 41228293, 2025). "Of the 602 participants with tumor sequencing results, 48.0% had AKT pathway alterations, most commonly PIK3CA mutations, while mutations in more than one gene were rare." (PMID 41226406, 2025). "Additionally, Glypican 3 (GPC3) is upregulated in tumors expressing specific PIK3CA mutations, and its overexpression induces aberrant synapse formation, exacerbating network hyperexcitability and accelerating the onset of seizures within the tumor microenvironment." (PMID 40076738, 2025). "Genetic events like mutations in PIK3CA, TERT alterations, and EGFR amplifications found in the primary tumor typically persist in the recurrent tumor." (PMID 40141375, 2025). "Clonality, spread with tumor dedifferentiation or metastatic PTC cells, and coexistence with TERTp, BRAF, RAS, and PIK3CA mutations were also investigated." (PMID 40272676, 2025). "PIK3CA mutations often co-occur with other alterations, including MAPK pathway genes and CDH1, further modulating tumor phenotype and immune landscape." (PMID 41425867, 2025). "Clinically, molecular biomarkers—including KRAS/NRAS/BRAF mutations, HER2 amplification, PIK3CA mutations, MSI/MMR status, and the tumor microenvironment—play an important role in therapeutic decision-making." (PMID 40805234, 2025). "Functionally, PIK3CA regulates several intracellular processes such as cellular transformation, tumor initiation, proliferation, and resistance to cell death." (PMID 41049266, 2025). "Some cases have shown additional genetic alterations, including activating mutations in PIK3CA and MTOR, suggesting potential molecular pathways involved in tumor growth." (PMID 41246635, 2025). "Oncogenic PIK3CA mutations activate the PI3K pathway, promote tumor initiation and development, and mediate resistance to anti-tumor treatments, making the mutant p110α an excellent target for cancer therapy." (PMID 39717717, 2025). "Decreasing mutant PIK3CA circulating tumor DNA (ctDNA) during treatment and estrogen receptor 1 (ESR1) mutations at baseline were related to a better prognosis, making them candidate biomarkers." (PMID 39717717, 2025).
tumor (continued). "Screening of the PCI-DB for naturally presented neoepitopes matching the patient’s tumor mutational profile, obtained from gene panel sequencing of a pulmonary metastasis, identified the peptide FDDIAYIRKALALDKTEQE (P1) derived from the PIK3CA T1025A mutation." (PMID 40234091, 2025). "For example, activating mutations in the PIK3CA gene have been extensively reported to aberrantly activate the PI3K/AKT signaling pathway, which in turn drives tumor cell proliferation and survival." (PMID 40018039, 2025). "PIK3CA inhibitors, such as alpelisib, have demonstrated the ability to suppress tumor growth by selectively targeting the overactive PI3K pathway and reducing IL-6 and IL-8 secretion." (PMID 40266213, 2025). "Compound 7p, in particular, displayed strong affinity for key cancer-related targets such as HSP90, IGF1R, HDAC2, CDK6, HDAC8, and PIK3CA, all of which are involved in tumour proliferation, survival, and metastasis." (PMID 41463373, 2025). "The aim of this study was to evaluate the diagnostic potential of a urinary tumor DNA detection panel, which included eight common point mutations in TERT, GPR126, FGFR3, and PIK3CA genes, in UBC." (PMID 41515564, 2025). "PTEN acts as a tumor suppressor by degrading PIP3; mutations in PIK3CA or PTEN loss lead to sustained pathway activation and tumor progression." (PMID 40861443, 2025). "The PTEN tumor suppressor regulates the PIK3CA/AKT1 pathway, and its inactivation significantly contributes to tumorigenesis and progression in hormone receptor-positive/HER2-negative (HR + /HER2 −) metastatic breast cancer (MBC)." (PMID 40931235, 2025). "To date, genetic profiling of BCAC cases has revealed mutation of PIK3CA, ATM, CYLD and NFKBIA14,23, but given the rarity of this tumour type and the small number of genes profiled, the roles of these mutations in tumour development is unclear." (PMID 40389436, 2025). "Specifically, BRD4, FLT3, and SIAH2 were upregulated in tumor tissues, whereas CS and PIK3CA were downregulated." (PMID 40696656, 2025). "The activation of bypass pathways, including HER2 amplification, MET amplification, and PIK3CA/KRAS mutations, promotes tumor survival and proliferation." (PMID 40733125, 2025). "Among its defining molecular alterations, PIK3CA mutations are frequently observed and are known to activate the PI3K/AKT/mTOR pathway, promoting tumor growth, survival, and endocrine resistance." (PMID 41425867, 2025). "Amplifications of CDK4/6, CCND2, PDGFRA, MYCN as well as RB1 mutation/homozygous deletion, MET alterations, PIK3R1/PIK3CA mutations, NOTCH1 mutations and TCF12 mutations are also associated with tumor progression & shorter survival in IDH mutant astrocytomas." (PMID 40949165, 2025). "Decisions should integrate patient preferences, tumor characteristics, prior therapy, and actionable biomarkers such as ESR1 and PIK3CA mutations, AKT pathway alterations, HER2-low/ultra-low status, and germline BRCA mutations." (PMID 41226406, 2025). "The BAX gene had different correlation coefficients in the three tumor types, while the PIK3CA gene had different correlation coefficients in two tumor types." (PMID 38463169, 2024). "Tumor-infiltrating lymphocytes (TIL) are a predictive biomarker for response to chemotherapy and immunotherapy, while phosphoinositide 3-kinase (PIK3CA) mutations predict response to targeted therapy." (PMID 39430073, 2024).
tumor (continued). "Targeted NGS with plasma circulating tumor DNA (ctDNA) detected PIK3CA M1004I and the EGFR 19 deletion." (PMID 38398169, 2024). "The isoform-specific PIK3CA inhibitor, alpelisib, has been used in in vitro studies to assess the anti-tumour effects on various canine tumour cell lines and is showing promising results." (PMID 38787171, 2024). "Mutations in the PIK3CA gene with a mutation rate from 11% to 75% typically result in increased PI3K enzyme activity, driving sustained tumor cell growth and proliferation while inhibiting apoptosis, thus conferring a growth advantage to the tumor cells." (PMID 39457636, 2024). "Approximately three quarters (76.9%) of PIK3CA wild-type tumours had pAKT levels that mimicked those of mutant lesions suggesting that AKT activity in MBCs is driven by genomic-dependent and independent events." (PMID 39322687, 2024). "In our study, we investigated the tumor mutation landscape between the two subgroups and noted the top four mutated genes: TTN, PIK3CA, KMT2C, and MUC4." (PMID 38672263, 2024). "It is promising that MTX-531 monotherapy led to tumor regressions in the two PIK3CA-mutant KRASG12C-mutant CRC PDX models studied here." (PMID 38992135, 2024). "This intricate signaling cascade orchestrated by PIK3CA has profound implications for tumor tropism." (PMID 39369580, 2024). "The mutation enhances peptide binding to HLA-A3 and the neoantigen drives T cell destruction of PIK3CA mutant tumors while leaving tumor cells expressing wild-type PIK3CA unharmed." (PMID 38854019, 2024). "The gain of function mutations in PIK3CA/AKT pathways, which are downstream of the HER2 receptor and are caused by a loss of the tumor suppressor PTEN, can confer resistance to HER2 inhibitors." (PMID 38256137, 2024). "The pan-PLK inhibitor volasertib showed profound anti-tumor activity in these CCND1-driven PDX models, with acquired resistance to palbociclib, including those with PIK3CA mutations." (PMID 39409880, 2024). "The PIK3CA gene encodes the catalytic subunit of phosphatidylinositol 3-kinase (PI3K), one of the most common genes in tumor malignancies." (PMID 38170269, 2024). "AKT monotherapy activity in PTEN protein deficient solid and haematological tumour cell lines is expected, as well as in tumour with activating alteration in PIK3CA and AKT1." (PMID 39284898, 2024).